PTH (parathyroid hormone)
Diseases named in the same sentence as PTH in open-access papers (continued):
Sharing a sentence is not in itself a finding about the gene and the disease.
Hypocalcemia (continued). "Patients with combined hypocalcemia and hypomagnesemia also show low levels of parathyroid hormone (PTH), and studies indicate that Mg deficiency inhibit the release of parathyroid hormone (PTH) in patients with coexisting hypocalcemia." (PMID 29610664, 2018). "Patients with Mg deficiency and hypocalcemia also present low levels of calcitriol (1.25-dihydroxyvitamin D) and together with impaired PTH secretion a reduced conversion of 25-hydroxyvitamin D to 1.25-dihydroxyvitamin D in the kidneys is suspected." (PMID 29610664, 2018). "In Cyp27b1–/–mice, 1α,25D3 deficiency and hypocalcemia caused secondary hyperparathyroidism, with plasma PTH reaching markedly high levels." (PMID 30281599, 2018). "Cyp27b1-knockout mice (Cyp27b1–/–mice) are congenitally deficient in 1α,25D3 and exhibit marked hypocalcemia and high parathyroid hormone levels, resulting in osteodystrophy involving bone hypocalcification and growth plate cartilage hypertrophy." (PMID 30281599, 2018). "On the other hand, severe AP is associated with “true” hypocalcaemia and low levels of parathyroid hormone." (PMID 30697165, 2018). "Elevated PTH levels associated with hypocalcemia and normal or high phosphate indicate an element of end-organ resistance to PTH, mimicking pseudo-hypoparathyroidism." (PMID 29699378, 2018). "A significant relationship was observed between postoperative PTH and hypocalcemia in patients with vitamin D deficiency or sufficiency (both P = 0.000)." (PMID 29100453, 2017). "Treatment of rats with aldosterone and 1% dietary salt increases urinary and intestinal calcium excretion causing hypocalcemia and increased PTH secretion." (PMID 29056965, 2017). "Cinacalcet is a type II calcimimetic and thus results in a risk of dose-dependent hypocalcaemia by reducing the parathyroid hormone." (PMID 28122587, 2017). "In patients with prostate cancer undergoing antiresoptive therapy for the treatment of bone metastases, vitamin D supplementation should be undertaken to normalize serum PTH levels and decrease the risk of antiresorptive-related hypocalcemia." (PMID 28390010, 2017). "The researchers in the present study have raised the iPTH cut-off level from 12 to 15.39 pg/ml in the development of a prediction for a single 1-hour PTH level in predicting the risk of development of hypocalcemia." (PMID 28955671, 2017). "Diets rich in K and Na induce metabolic alkalosis, interfering with tissue sensitivity to parathyroid hormone, and diets rich in Cl and S (anionic salts) cause metabolic acidosis, reducing the risk of hypocalcemia." (PMID 28660195, 2017). "Our study has revealed Dsk7 mice to have hypocalcemia and reduced PTH concentrations, which are caused by a gain-of-function Gna11 mutation that leads to upregulation of CaSR-mediated Ca2+i and MAPK signaling responses." (PMID 28194447, 2017). "Vitamin D deficiency has been claimed to influence postoperative hypocalcemia and interfere with the accuracy of PTH prediction, ostensibly by causing secondary hyperparathyroidism and false elevation of PTH." (PMID 28955671, 2017). "Hypocalcemia secondary to peripheral PTH resistance or decreased PTH secretion, as in our case, is further complicated by the loss of PTH stimulation of 1-alpha-hydroxylation of vitamin D in the kidney, thereby worsening the vitamin D deficiency." (PMID 27190662, 2016). "The final cost of lowering phosphorus is an increase in the levels of FGF23 and hypocalcaemia, this last one causing an increase in the synthesis and liberation of parathyroid hormone (PTH) 19,20." (PMID 27821896, 2016). "Hypoparathyroidism causes symptomatic or asymptomatic hypocalcemia by normal or inappropriately low levels of parathyroid hormone (PTH) secretion." (PMID 26800885, 2016). "This delay in imprinting of GNAS in proximal renal tubules leads to delay in PTH resistance and also to the clinical and biochemical expression of its associated manifestations such as hypocalcemia and seizures." (PMID 27467896, 2016).
Hypocalcemia (continued). "Hypoparathyroidism (HP) and pseudohypoparathyroidism (PHP) are a group of heterogeneous conditions in which hypocalcemia and hyperphosphatemia occur as a result of deficient parathyroid hormone (PTH) secretion or end‐organ PTH resistance." (PMID 27415614, 2016). "By contrast, the patient in the present study exhibited normal PTH values, which perturbed diagnosis of the underlying cause of the severe hypocalcemia." (PMID 26622568, 2015). "The present report describes a case of severe hypocalcemia and associated heart failure observed as a clinical presentation of subsequently diagnosed bone-metastatic breast cancer in a patient with normal PTH values." (PMID 26622568, 2015). "Even though magnesium concentrations were not measured in the foals of this study, hypomagnesemia reduces PTH secretion and action, and has been linked to hypocalcemia, hypovitaminosis D, and hyperphosphatemia." (PMID 26046642, 2015). "Pseudohypoparathyroidism type 1a (PHP1a) is characterized by hypocalcaemia and hyperphosphatemia due to parathyroid hormone resistance, in association with the features of Albright's hereditary osteodystrophy (AHO)." (PMID 25219572, 2015). "In breast cancer patients, hypocalcemia is markedly more unusual than in prostate cancer, and appears to be more frequently associated with the abnormal endocrine activity induced by low parathyroid hormone (PTH) levels." (PMID 26622568, 2015). "Our center currently categorizes post-thyroidectomy patients as high risk for developing hypocalcemia based on a 1 hr PTH of less than 12 pg/ml." (PMID 24476535, 2014). "A single 1-hour post-thyroidectomy PTH level is a very useful way to stratify thyroidectomy patients into high and low risk groups for development of hypocalcemia." (PMID 24476535, 2014). "Of the 125 patients, 31 (25%) had a 1 hr PTH level < 12 pg/ml, and were therefore deemed to be at high risk for developing hypocalcemia." (PMID 24476535, 2014). "Secondary hyperparathyroidism is characterized by elevated parathyroid hormone (PTH) levels in response to hypocalcemia and is often caused by chronic kidney disease." (PMID 24772087, 2014). "Niney-four patients (75%) had a 1 hr PTH level ≥ 12 pg/ml, and were thus classified as low risk for developing hypocalcemia." (PMID 24476535, 2014). "Blood laboratory study results indicated serum hypocalcemia, hypomagnesemia, and hyperphosphatemia associated with a low parathyroid hormone level." (PMID 25280468, 2014). "A single 1-hour post-thyroidectomy PTH level is a valuable tool for stratifying patients as to their level of risk for developing hypocalcemia." (PMID 24476535, 2014). "Our study showed that vitamin D deficient rats presented hypophosphatemia, hypocalcemia and higher levels of PTH." (PMID 25048368, 2014). "It is important to note that the two low risk patients that developed hypocalcemia had borderline PTH levels of 12 and 13 pg/ml." (PMID 24476535, 2014). "CKD exerts an important impact on PTH, as the impairment of Pi excretion and hypocalcemia in CKD stimulates PTH synthesis and secretion, causing secondary hyperparathyroidism." (PMID 23760058, 2013). "Once hypocalcemia is found, major causes of late-onset neonatal hypocalcemia should be investigated by obtaining a basic metabolic panel, liver function tests, PTH, 25(OH)D." (PMID 24072092, 2013). "Although PTX is effective in lowering serum PTH, it also commonly results in persistent, inappropriately low PTH levels with the inherent risk of hypocalcemia and adynamic bone disease." (PMID 23819622, 2013). "The cause of hypocalcemia, in spite of hypocalciuria in GS, is due to hypomagnesaemia induced (a) impaired synthesis, secretion of PTH (b) end organ resistance to PTH and vitamin D." (PMID 24171002, 2013). "This is unsurprising as magnesium deficiency in particular is a known cause of hypocalcemia due to impaired parathyroid hormone secretion and end organ resistance." (PMID 23734769, 2013).
Hypocalcemia (continued). "Septic patients are at particular risk of hypocalcemia and this has been linked to both the bacteremic state and the effect of inflammatory mediators on parathyroid hormone secretion and function." (PMID 23734769, 2013). "When calcium intake is low, small degrees of hypocalcemia stimulate PTH secretion to cause the release of calcium into ECF, thus correcting the hypocalcemia." (PMID 24084054, 2013). "Hypocalcaemia occurs in vitamin D deficiency and this stimulates parathyroid hormone (PTH) which in turn depletes calcium from the bone causing osteopenia." (PMID 23919113, 2013). "Calcium metabolism is under control through the coordinated actions of parathyroid hormone (PTH) and activated vitamin D, and the most common cause of hypocalcemia in primary care is vitamin D deficiency." (PMID 23710380, 2013). "Maternal Ca, phosphorus and PTH levels were assessed to help determine the cause of hypocalcemia in our patient." (PMID 24072092, 2013). "Hypomagnesemia is often associated with hypocalcemia due to both lower PTH secretion and end-organ resistance." (PMID 22394705, 2012). "Patients with PHP1A develop PTH resistance and associated hypocalcemia and hyperphosphatemia, features attributable to imprinted expression of GNAS." (PMID 23284784, 2012). "Both magnesium deficiency and excess inhibits parathyroid hormone secretion resulting in hypocalcemia; and the hypocalcemia due to deficiency is corrected by magnesium supplements." (PMID 23194380, 2012). "Given that only 3.1 % of patients had mild hypocalcemia, it would seem a reasonable approach to discharge patients with PTH-SC >1 pmol/L on the same day of surgery as the risk of a life-threatening hypocalcemic episode is unlikely." (PMID 22399155, 2012). "It is well known that vitamin D deficiency causes an increase in bone resorption (presumably from the rise in PTH caused by hypocalcaemia)." (PMID 22785268, 2012). "It would be reasonable to discharge those with PTH-SC >1 pmol/L on the same operative day as the risk of life-threatening hypocalcemia would seem unlikely." (PMID 22399155, 2012). "In adult Oed mice the mutation also results in resistance to PTH, hypocalcemia, hyperphosphatemia and obesity; findings consistent with loss of function of Gsα." (PMID 23284784, 2012). "In young adult Oed mice the Gnas mutation results in resistance to PTH, hypocalcemia and hyperphosphatemia." (PMID 23284784, 2012). "In the multivariate analysis, low preoperative adjusted calcium (p = 0.041) and low PTH-SC (p = 0.001) were the two independent variables associated with hypocalcemia." (PMID 22399155, 2012). "Intact parathyroid hormone (i-PTH) testing is a proven effective method to detect patients at risk for postoperative symptomatic hypocalcemia." (PMID 23108824, 2012). "Although many studies have looked into the correlations between postoperative i-PTH levels and risk of hypocalcemia, very few tried to establish the obvious resulting clinical applications, once test results and conclusions in these studies vary significantly." (PMID 23108824, 2012). "Hypocalcemia is considered to result from the loss of the effects of PTH on calcium reabsorption from the distal nephron or reduced bone resorption." (PMID 23133549, 2012). "This study analyzed the differences between immediate, late, and serial i-PTH testing in determining the risk of hypocalcemia." (PMID 23108824, 2012). "This study looked into the correlation between serum i-PTH levels measured at different times after total thyroidectomy and the risk of symptomatic hypocalcemia." (PMID 23108824, 2012). "Srivastava was the first to draw attention to the possibility that the elevated PTH levels associated with hypocalcemia and normal P indicate an element of end−organ resistance to PTH, mimicking PHP." (PMID 21274319, 2010).
Hypocalcemia (continued). "During the treatment the patient developed hypocalcemia associated with high plasma levels of valproic acid, parathyroid hormone and alkaline phosphatase, indicating increased bone turnover." (PMID 19829950, 2009). "Vitamin D deficiency can lead to an increase in PTH as a compensatory mechanism for hypocalcemia." (PMID 41601884, 2026). "The main causes of hypocalcemia in neonates with asphyxia include increased phosphate load due to cellular damage, increased calcitonin production, renal failure, and decreased parathyroid hormone (PTH) secretion." (PMID 41007076, 2025). "Diagnostic performance of ALP and preoperative PTH for predicting postoperative hypocalcemia." (PMID 40517023, 2025). "Similarly, a case series reported symptomatic hypocalcemia and high PTH levels in adolescents during the pandemic, directly linked to nutritional vitamin D deficiency." (PMID 40709988, 2025). "Hypocalcaemia and hypokalaemia in this context likely reflect mineral sequestration due to tissue injury, inflammation-induced loss, or impaired hormonal regulation (e.g., parathyroid hormone)." (PMID 41011783, 2025). "The homozygous R25CPTH mutation was identified in patients who presented with hypocalcemia and hyperphosphatemia, despite elevated PTH levels, and the mutation was found to impact the bioactive region of PTH." (PMID 40153305, 2025). "Although uncommon, the association between elevated parathyroid hormone, hypocalcaemia, and hypertension has been described, and this case reinforces the need to consider even rare aetiologies when evaluating young patients with hypertensive crises and target organ damage." (PMID 41257110, 2025). "In contrast, secondary hypocalcemia with elevated PTH may arise from chronic renal disease, vitamin D deficiency, or resistance to PTH action (pseudohypoparathyroidism [PHP])." (PMID 41322012, 2025). "A spontaneous mouse model of ADH1, the Gprc2aNuf mouse (referred to as Nuf), has a GOF Leu723Gln Casr mutation and manifests hypocalcemia, hyperphosphatemia, reduced serum PTH and ectopic calcifications most notably in the ocular lens, but lacks hypercalciuria." (PMID 39658204, 2025). "Conditions like hypocalcemia or vitamin D deficiency lead to increased PTH (hyperparathyroidism)." (PMID 40709988, 2025). "Conversely, patients with severe calciphylaxis or extensive osteitis fibrosa cystica may favor TPTX to ensure definitive PTH reduction, despite the risk of transient hypocalcemia." (PMID 40725638, 2025). "A drop in 1, 25dihydroxyvitamin D may cause hypocalcemia, leading to continuous PTH secretion and consequently resulting in secondary hyperparathyroidism." (PMID 41217540, 2025). "Therefore, compared with a reduced PTH level, a decreased 1,25(OH)2D level is a relatively greater risk factor for postoperative hypocalcemia after TT." (PMID 40786097, 2025). "Lack or insufficient action of PTH on effector organs causes hypocalcemia and hyperphosphatemia." (PMID 40444234, 2025). "The possible causes include: 1) physiological changes of PTH: Postoperative hypocalcemia activates calcium receptors in parathyroid cells, prompting increased PTH secretion as an adaptive compensatory response.2) hungry bone syndrome (HBS): Physiologic or low doses of PTH promote bone formation." (PMID 41036144, 2025). "The sudden drop in PTH levels leads to a sharp decline in bone resorption and a corresponding increase in calcium and phosphate deposition into bone tissue, often causing significant and prolonged hypocalcemia." (PMID 40959118, 2025). "Hypocalcemia due to deficiency of the active form of vitamin D3 has markedly upregulated PTH production in Najdi lambs, which could induce further physiological disorders." (PMID 40231299, 2025). "Therefore, this condition is associated with hypocalcemia, low urinary calcium, elevated PTH, hypophosphatemia, hyperphosphaturia, and elevated 1,25(OH)2D." (PMID 40241811, 2025).
Hypocalcemia (continued). "Age, sex, serum magnesium, vitamin D, high-risk pathological subtype, parathyroid injury, and the PTH level may be associated with hypocalcemia after TT but the evidence is still controversial and sometimes contradictory." (PMID 40786097, 2025). "Additionally, hypocalcemia in septic neonates has been associated with the systemic inflammatory response, altered parathyroid hormone secretion, and inadequate calcium intake." (PMID 41028664, 2025). "Given that hypocalcemia is common in patients with HD, it may induce neurotoxicity, neurotransmitter imbalance, and excessive parathyroid hormone stimulation, alongside 1,25(OH)2D3 deficiency." (PMID 40229685, 2025). "HP represents a clinical syndrome resulting from either deficient PTH secretion or impaired hormonal action, manifesting as a characteristic triad of hypocalcemia, hyperphosphatemia, and consequent clinical sequelae, including soft tissue calcification and heightened neuromuscular excitability." (PMID 40590356, 2025). "In some atypical cases, GS may also be associated with hypocalcemia and secondary elevations in PTH levels, further complicating differential diagnosis." (PMID 40893942, 2025). "Therefore, this review aims to identify and summarize the available evidence on impaired PTH secretion despite hypocalcemia secondary to magnesium deficiency." (PMID 40740723, 2025). "Gain-of-function mutations of the calcium-sensing receptor (CaSR) result in autosomal dominant hypocalcemia type 1 (ADH1), which may cause symptomatic hypocalcemia with low parathyroid hormone concentrations." (PMID 40086735, 2025). "The loss of the compensatory role of PTH in secondary hyperparathyroidism due to Vit.D deficiency and the remaining need for bone restoration may increase the risk of hypocalcemia." (PMID 38259695, 2024). "Previous research has demonstrated that thermal ablation could maintain a relatively high PTH level, decreasing the risk of hypocalcemia than PTX." (PMID 39697216, 2024). "FGF23 also suppresses 1-α-hydroxylase, intensifying the unavailability of biologically active vitamin D. So, the net effect of hypovitaminosis D or dietary deficiency of calcium is hypocalcemia, hypophosphatemia, decreased osteoblastic activity, and increased levels of PTH." (PMID 39301310, 2024). "Close monitoring of postoperative PTH levels, administering perioperative calcium and vitamin D supplements, and tracking perioperative calcium level changes are key factors for the early identification of patients at risk of hypocalcemia." (PMID 39258042, 2024). "Furthermore, this decrease in circulating active vitamin D levels causes slight hypocalcemia, which increases parathyroid hormone levels, further worsening hypophosphatemia owing to its phosphaturic nature." (PMID 39703298, 2024). "Hyperuricemia is a strong contributor to MBD; it is a very common condition in patients with CKD and is characterized by hyperphosphatemia, hypocalcemia, and elevated levels of PTH, which is associated with bone disease, vascular calcifications, and risk of all-cause and cardiovascular death." (PMID 39768960, 2024). "However, if the serum magnesium levels fall below 1.2 mg/dL or 0.06 mmol/L, it leads to a decline in the PTH secretion and ultimately causes hypocalcemia." (PMID 39479146, 2024). "Probably, symptomatic hypocalcemia associated with low PTH levels might represent an alternative endpoint in defining postoperative HypoPTH, but it should be validated only by prospective studies." (PMID 39199638, 2024). "In AlqahtaniSM’s study, the occurrence of hypocalcemia in patients after unilateral thyroidectomy may be related to low preoperative calcium levels, parathyroid tissue loss, and postoperative decreased parathyroid hormone levels." (PMID 39544238, 2024). "Despite normal vitamin D and PTH levels, COVID-19 was identified as the cause of hypocalcemia." (PMID 39262524, 2024).